NRAS (NRAS proto-oncogene, GTPase)
Diseases named in the same sentence as NRAS in open-access papers (continued):
Sharing a sentence is not in itself a finding about the gene and the disease.
Myelodysplasia (3 papers, 2021 to 2025). Clonal hematopoietic stem cell disorders characterized by dysplasia (ineffective production) in one or more hematopoietic cell lineages, leading to anemia and cytopenia. "The presence of poor-risk cytogenetic abnormalities, the presence of other mutations in myeloid genes, and the presence of mutations in myelodysplasia-related genes and/or mutations in NRAS/KRAS did not seem to have a significant impact on the EFS and OS." (PMID 40002262, 2025). "However, the presence of adverse risk cytogenetics and mutations in myeloid genes, myelodysplasia-related genes and/or NRAS/KRAS had no impact on the EFS and OS." (PMID 40002262, 2025).
myelofibrosis (3 papers, 2022 to 2023). A partial or complete replacement of the bone marrow stroma by fibrous tissue. "Concerning the prognostic impact of RAS mutations, in a recent study that included 723 patients with PMF and post-PV or post-ET myelofibrosis (MF), oncogenic NRAS/KRAS mutations conferred a high risk of developing sAML, leading to reduced survival." (PMID 37841434, 2023).
neurofibromatosis type 1 (3 papers, 2020 to 2021). A clinically heterogeneous, neurocutaneous genetic disorder characterized by cafe-au-lait spots, iris Lisch nodules, axillary and inguinal freckling, and multiple neurofibromas. "Many have neurofibromatosis type I (NF1) and NRAS mutations, and sporadic BRAF V600K mutations are also seen." (PMID 32028967, 2020).
non-Hodgkin lymphoma (3 papers, 2008 to 2023). Distinct from Hodgkin lymphoma both morphologically and biologically, non-Hodgkin lymphoma (NHL) is characterized by the absence of Reed-Sternberg cells, can occur at any age, and usually presents as a localized or generalized lymphadenopathy associated with fever and weight loss.
oral cancer (3 papers, 1991 to 2020). "Some of these genes, including AKT, BRAF, PIK3CA, NRAS, GSK3, CNND1, etc., are involved not only in oral cancers but, generally, in several solid tumors." (PMID 31052345, 2019). "In the oral cancer cells (HSC4, OSC19) that were used in this study, high expression of EGFR was confirmed, but no mutations of BRAF, HRAS, KRAS, and NRAS were observed." (PMID 32878053, 2020).
papilloma (3 papers, 2016 to 2025). A benign epithelial neoplasm that projects above the surrounding epithelial surface and consists of villous or arborescent outgrowths of fibrovascular stroma. "It is suggested that NRAS play a critical role in the progression of CA, especially in forming papillomas." (PMID 30225000, 2018).
renal cell carcinoma (3 papers, 2016 to 2023). "Based on the KEGG analysis, G6PD was enriched in central carbon metabolism in cancer, and HRAS and NRAS could be involved in many signaling pathways, such as AGE-RAGE signaling pathway in diabetic complications, human cytomegalovirus infection and renal cell carcinoma." (PMID 37143953, 2023).
T-cell leukemia (3 papers, 2019 to 2023). A malignant disease of the T-lymphocytes in the bone marrow, thymus, and/or blood. "Significantly, whilst TCF7-SPI1 fusions are insufficient for frank T-cell leukemia development, these clinical cases are often coincident with NRAS mutations suggesting the potential for oncogenic cooperation." (PMID 34230493, 2021). "In conclusion, we have shown that TCF7-SPI1 cooperates with NRAS (G12D) to drive an aggressive immature T-cell leukemia in vivo and that it is possible to target this fusion protein by inhibiting protein-protein interactions between TCF1 and β-catenin." (PMID 34230493, 2021).
triple-negative breast carcinoma (3 papers, 2015 to 2021). An invasive breast carcinoma which is negative for expression of estrogen receptor (ER), progesterone receptor (PR), and human epidermal growth factor receptor 2 (HER2). "In another case (patient P0030), an activating mutation in NRAS was identified; activating mutations in NRAS are uncommon in triple negative breast cancer." (PMID 27245685, 2016). "It is of note that high MSLN expression was linked to several key molecular features in the cancer types analyzed, such as triple negative breast cancer and RAS (KRAS or NRAS) mutations." (PMID 33917081, 2021).
vaginal melanoma (3 papers, 2015 to 2025). A primary malignant neoplasm of the vagina composed of malignant melanocytes. "Conversely, NRAS mutations are uncommon in vulval melanomas (10.2%) and appear to have a comparatively higher incidence in vaginal melanomas." (PMID 41295253, 2025). "It was reported that NRAS mutations and PD-L1 expression were most common in primary vaginal melanomas and can be probably used as therapeutic targets." (PMID 33553243, 2020). "Specifically, in a study involving 30 patients with vulvar and vaginal melanomas, BRAF and NRAS mutations exhibited a 7% and 10% frequency, respectively, while similar low frequencies of BRAF mutation ranging from 0% to 12.5% have been detected in other studies." (PMID 25695059, 2015).
acromegaly (2 papers, 2023). Acromegaly is an acquired disorder related to excessive production of growth hormone (GH) and characterized by progressive somatic disfigurement (mainly involving the face and extremities) and systemic manifestations. "Conversely, a recent study concluded that the BRAF V600E mutation was present in 14.3% of the patients diagnosed with DTC and acromegaly, while none of them harbored the NRAS codon 61 mutation." (PMID 37374352, 2023).
acute monocytic leukemia (2 papers, 2021 to 2023). Acute monoblastic leukemia (AML-M5), is one of the most common subtypes of acute myeloid leukemia (AML) that is either comprised of more than 80% of monoblasts (AML-M5a) or 30-80% monoblasts with (pro)monocytic differentiation (AML-M5b). "In contrast, LZTR1 deficiency increased RIT1, KRAS, MRAS, and NRAS expression in fetal liver and acute monocytic leukemia cells." (PMID 37626065, 2023).
acute promyelocytic leukemia (2 papers, 2017 to 2020). An aggressive form of acute myeloid leukemia (AML), characterized by arrest of leukocyte differentiation at the promyelocyte stage, due to a specific chromosomal translocation t(15;17) in myeloid cells. "Firstly, we used the HL-60 (human promyelocytic leukaemia, NRas mutated) cell line for general cytotoxicity screening of all compounds." (PMID 33371382, 2020). "Both KRAS and NRAS expressions were not correlated with CR rate among non-acute promyelocytic leukemia (APL) patients [43% (34/79, KASlow) vs 29% (10/34, KRASlow), P=0.210 and 41% (32/79, NRASlow) vs 35% (12/34, NRAShigh), P=0.677]." (PMID 29029494, 2017).
anaemia (2 papers, 2019 to 2024).
anal squamous cell carcinoma (2 papers, 2016 to 2022). A squamous cell carcinoma (SCC) arising from the anal canal or the anal margin (perianal skin). "Moreover, cetuximab may be an effective treatment for anal squamous cell carcinoma because EGFR is overexpressed in many cases, while KRAS, NRAS, and BRAF mutations are not observed in most cases." (PMID 35723765, 2022).
anaplastic astrocytoma (2 papers, 2021 to 2024). "In anaplastic astrocytoma, RAS mutations typically involve alterations in the HRAS, KRAS, or NRAS genes." (PMID 39459475, 2024). "Another anaplastic astrocytoma, IDH-wildtype, showed NRAS mutation." (PMID 34525976, 2021).
asthma (2 papers, 2021 to 2025). "Analysis of tight‐junction gene sets revealed the reduced expression of a whole cluster of genes such as OCLN, CLDN3, CLDN4, NRAS, HCLS1, MYH10 in virus‐infected cells from patients with asthma in comparison to the controls." (PMID 39466641, 2025).
autism (2 papers, 2015 to 2018). Persistent deficits in social interaction and communication and interaction as well as a markedly restricted repertoire of activity and interest as well as repetitive patterns of behavior. "Another targeted gene that was associated with innate immune response is NRAS target for chr1:115259341 novel regulatory variant for autism." (PMID 29745862, 2018). "NRAS plays roles in the regulation of long-term neuronal synaptic plasticity and transmission and is considered a candidate gene for autism." (PMID 26061495, 2015).
bone tumors (2 papers, 2012 to 2024). "However, there has been no report about the relationship between bone tumors and NRAS." (PMID 23199169, 2012).
colon adenoma (2 papers, 2017 to 2019). An adenoma that arises from the colon.
colorectal adenoma (2 papers, 2018 to 2020). An adenoma that arises from the colon or rectum. "KRAS/NRAS mutations in colorectal adenomas are the only occurrence where we cannot find discriminable protein profiles between cases that would be treated and those which would not." (PMID 30442178, 2018).
esophageal melanoma (2 papers, 2015 to 2021). A melanoma affecting the esophageal wall. "Our finding is similar to the published data on esophageal melanomas, which harbored NRAS mutations in 30% of cases." (PMID 34102999, 2021).
follicular papillary carcinoma (2 papers, 2020 to 2023). "In our study, NRAS was an independent factor for cN0 CLNM (p<0.001), perhaps just because of a specific subset, such as follicular papillary carcinoma." (PMID 36817603, 2023).
head and neck squamous cell carcinoma (2 papers, 2017 to 2019). A squamous cell carcinoma that arises from any of the following anatomic sites: lip and oral cavity, nasal cavity, paranasal sinuses, pharynx, larynx, and salivary glands.
hemangioma (2 papers, 2022 to 2025). A benign vascular lesion characterized by the formation of capillary-sized or cavernous vascular channels. "NRAS was the only member of the RAS family included in the present study which was downregulated in both infantile and proliferating hemangioma." (PMID 35740845, 2022).
hypothyroidism (2 papers, 2015 to 2020). Abnormally low levels of thyroid hormone. "At a gene level, PTPN11, NRAS, RASA2, SOS2, MAP2K1, and RAF1 were significantly associated with hypothyroidism, diastolic and systolic BP, birth weight, growth abnormality, subcutaneous adipose tissue, standing/sitting height ratio and body mass index." (PMID 33226994, 2020).
invasive breast carcinoma (2 papers, 2022 to 2024). A carcinoma that infiltrates the breast parenchyma. "In this study, we investigated whether NRAS expression at the DCIS stage can control transition from luminal DCIS to basal-like invasive breast cancers." (PMID 36258226, 2022). "Additionally, although recent evidence has reported a role for overexpression of wild-type KRAS, HRAS, or NRAS in different carcinomas, including invasive breast cancers, a driver role in their wild-type form for tumorigenesis in in vivo models has not yet been demonstrated." (PMID 38987766, 2024). "NRAS mRNA levels were also determined by fluorescence in situ hybridization in patient tumor microarrays (TMAs) with concurrent normal, DCIS, and invasive breast cancer, and association of NRAS mRNA levels with DCIS and invasive breast cancer was assessed by paired Wilcoxon signed-rank test." (PMID 36258226, 2022).
iris melanoma (2 papers, 2019 to 2020). A uveal melanoma that arises from the iris. "In contrast to posterior UM, mutations in BRAF (0–47%) and NRAS have been described in iris melanoma, although the frequency of their presence is unclear, and they might not represent driver mutations." (PMID 32718045, 2020).
large cell carcinoma (2 papers, 2009 to 2015). A malignant epithelial neoplasm composed of large, atypical cells. "In contrast, NRAS mutant large cell carcinoma cell line exhibited lower level of MAPK signaling and prominent activity of basophilic kinases including AKT40." (PMID 26278961, 2015).
laryngeal squamous cell carcinoma (2 papers, 2021 to 2024). A squamous cell carcinoma that arises from the larynx. "SNPs in the 3'UTR region of NRAS and KRAS genes can play an important role in the progression of cancers including laryngeal squamous cell carcinoma by affecting gene expression and RNA regulatory interactions." (PMID 39867023, 2024).
Lupus (2 papers, 2022 to 2024). "Lupus-like symptoms with monocytosis reminded us of Ras-associated autoimmune leukoproliferative disorder, and Sanger sequencing of KRAS and NRAS genes from the patients’ peripheral blood mononuclear cells (PBMC), sorted CD3+ lymphocytes and CD14+ monocytes, and cerebrospinal fluid were performed." (PMID 35361277, 2022).
malignant salivary gland tumours (2 papers, 2015 to 2018). "Importantly, the PIK3CA in case 6 and NRAS in case 1 and 3 are rational candidates for off-label targeted treatments and the NOTCH1 mutation in case 1 is eligible for inclusion in an ongoing clinical trial for advanced salivary gland cancers (clinicaltrials.gov identifier: NCT020697309)." (PMID 29731974, 2018).
medullary carcinoma (2 papers, 2022 to 2024). "Mutations occur in any of the RAS genes (NRAS > HRAS > KRAS in nodules/tumors of follicular cells, HRAS > KRAS > NRAS in medullary carcinoma)." (PMID 38108848, 2024).
melanocytic neoplasm (2 papers, 2016 to 2021). "pTERTm are suggested to have synergistic effects to promoter tumour cell proliferation with activating BRAF or NRAS mutations, which have been proposed to be driver mutations in the development of cutaneous melanocytic neoplasms." (PMID 26799744, 2016).
mismatch repair deficiency (2 papers, 2021 to 2023).
mucinous adenocarcinoma of the appendix (2 papers, 2023 to 2024). Mucinous adenocarcinoma of the appendix is a very rare, slow growing, well-differentiated epithelial neoplasm of the appendix characterized by abundant mucin production. "Mutated NRAS was found in only one (0.4%) specimen, a mucinous appendiceal adenocarcinoma." (PMID 39435876, 2024).
neurocutaneous disorder (2 papers, 2024). "The presence of the mutations in non-affected tissue is indicative of a neurocutaneous syndrome, which is caused by a post-zygotic missense variant of NRAS." (PMID 39273574, 2024).
Noonan syndrome 6 (2 papers, 2016 to 2022). Any Noonan syndrome in which the cause of the disease is a mutation in the NRAS gene. "Variants of NRAS have been described as causing Noonan Syndrome,Type 6 (OMIM #613224), an autosomal dominant disorder." (PMID 27561113, 2016).
Obesity (2 papers, 2016 to 2022). Accumulation of substantial excess body fat. "Moreover, accumulation of DNA mutations, such as APC, KRAS, NRAS, BRAF, or PIK3CA, makes obesity a multifactor phenomenon involved in CRC initiation and progression." (PMID 36235624, 2022). "Moreover, accumulation of DNA mutations, as in APC, KRAS, NRAS, BRAF, or PIK3CA, and insulin secretion sets obesity as a multifactor phenomenon involved in CRC initiation and aggressive development." (PMID 26801617, 2016).
pancreatic neuroendocrine tumor (2 papers, 2016 to 2021). Pancreatic endocrine tumor, also known as pancreatic neuroendocrine tumor (PNET), describes a group of endocrine tumors originating in the pancreas that are usually indolent and benign, but may have the potential to be malignant. "The human pancreatic NET cell line BON1 harbors a mutation in NRAS, while the human pancreatic NET cell line QGP-1 harbors a mutation in KRAS." (PMID 33807122, 2021). "However, the human pancreatic neuroendocrine tumor cell line BON1 harbors a mutation in NRAS, while the human pancreatic neuroendocrine tumor cell line QGP-1 harbors a mutation in KRAS." (PMID 33807122, 2021).
rectal adenocarcinoma (2 papers, 2018 to 2021). "In the PanCanAtlas, KRAS mutations were widespread in PAAD (72%), COAD (45%), rectum adenocarcinoma (READ, 42%), and LUAD (31%), while NRAS mutations were common in SKCM (31%)." (PMID 29617658, 2018).
renal fibrosis (2 papers, 2021 to 2023). A final common manifestation of a wide variety of chronic kidney diseases characterized by glomerulosclerosis and tubulointerstitial fibrosis. "N-Ras was also found to promote renal fibrosis by participating in TGF-β1 induced proliferation and the synthesis of collagen and fibronectin, whereas the function of NRAS in IPF has not been studied." (PMID 34671612, 2021).
sarcomatoid carcinoma (2 papers, 2023 to 2025). A malignant epithelial neoplasm characterized by the presence of spindle cells and anaplastic morphologic features. "This may be of pathological and clinical importance because pathologists and oncologists facing sarcomatoid carcinoma may be aware that sarcomatoid features could be associated with NRAS mutations, among other well-known mutations." (PMID 40423070, 2025).
soft tissue sarcoma (2 papers, 2018 to 2023). A malignant neoplasm arising from muscle tissue, adipose tissue, blood vessels, fibrous tissue, or other supportive tissues excluding the bones. "Because oncogenic NRAS also drives ERK signalling in cancer, we tested the effect of NRAS knockdown in HT-1080 and RD soft tissue sarcoma cell lines (which both contain a Q61 NRAS mutation) and found that NRAS knockdown sensitised cells to ER-stress." (PMID 29329780, 2018). "•In soft tissue sarcoma cell lines with constitutively active NRAS, inhibition of MEK/ERK, or knockdown of NRAS, sensitises cells to ER-stress." (PMID 29329780, 2018).
Spitz nevi (2 papers, 2021 to 2023). "Indeed, a worrisome melanocytic lesion with Spitz nevus features should lack BRAF and NRAS mutations and harbor one of these typical initiating genetic drivers to be classified as AST or Spitz melanoma." (PMID 34830218, 2021).
spitzoid melanoma (2 papers, 2015 to 2021). "Finally, the third group is Spitzoid melanoma, where NRAS and BRAF mutations are absent and the lesions often have a less aggressive clinical course." (PMID 33996584, 2021).
steatosis (2 papers, 2023 to 2024). Increased lipid within the cytoplasm of cells. "Examination of non-tumor regions of H&E-stained slides found extensive steatosis with hypertrophy in both SB/AKT/c-Met + saline and SB/AKT/NRas + saline as previously reported; histological steatosis score was significantly increased." (PMID 39254423, 2024).
urothelial carcinoma (2 papers, 2016 to 2023). A malignant neoplasm derived from the transitional epithelium of the urinary tract (urinary bladder, ureter, urethra, or renal pelvis). "Our analysis revealed one single UrC with NRAS mutation (1/22, 5%), suggesting, that these mutations are rare also in UrC similar to those of CRC and urothelial carcinoma (5% and 1% respectively)." (PMID 27283768, 2016).
uterine corpus endometrial carcinoma (2 papers, 2021 to 2022). A endometrial carcinoma (disease) that involves the body of uterus. "The analysis showed that mutation in the NRAS gene would significantly affect the survival of patients having uterine corpus endometrial carcinoma (p-value = 0.0282)." (PMID 36430761, 2022).